POSTN (periostin)
Diseases named in the same sentence as POSTN in open-access papers (continued):
Sharing a sentence is not in itself a finding about the gene and the disease.
glioblastoma (43 papers, 2008 to 2026). The most malignant astrocytic tumor (WHO grade IV). "Further, overexpression of the direct p73 target, POSTN, that encodes the integrin-binding protein restores the invasion ability of glioblastoma cells after p73 depletion." (PMID 34944027, 2021). "POSTN is secreted by glioblastoma stem cells to recruit tumor-associated macrophages in order to promote malignant growth and regulate tumor resistance to anti-angiogenic therapy." (PMID 30626092, 2019). "Using a gene microarray, we identified POSTN as a direct transcriptional target of p73 that is strongly down regulated in glioblastoma cells upon p73 loss." (PMID 26930720, 2016). "Taken together we have shown that p73 ablation leads to morphological changes associated with a differentiated phenotype in glioblastoma cells, that leads to a decrease in their invasion ability through inactivation of the p73/POSTN axis." (PMID 26930720, 2016). "We chose POSTN (Periostin), as it has previously been implicated in glioblastoma malignancy and to be important for EMT and cancer metastasis." (PMID 26930720, 2016). "Glioblastoma-secreted periostin encoded by POSTN recruited M2 macrophages to promote cancer growth." (PMID 36494582, 2023). "Supporting evidence from glioblastoma stem cells shows that POSTN enhances self-renewal and malignancy via activation of the αvβ3/PI3K/AKT/β-catenin/FOSL1 pathway, upregulating key stemness markers such as CD133, Nestin, and SOX239." (PMID 40520021, 2025). "Glioblastoma stem cells (GSCs) secrete periostin (POSTN), which acts as a chemoattractant for circulating monocytes that infiltrate the tumor and differentiate into M2-like macrophages via integrin αvβ3 signaling." (PMID 40076738, 2025). "These factors, produced exclusively by CSCs, particularly periostin, are secreted preferentially by CSCs in glioblastomas and cholangiocarcinomas to enhance TAM recruitment." (PMID 39068459, 2024). "For example, in glioblastoma and cholangiocarcinoma, CSCs can also recruit macrophages by specifically secreting POSTN that binds to the macrophage surface receptor integrin αvβ3." (PMID 38613794, 2024). "In MG3, genes involved in endothelial regulation (ESM1, APLN, ALCAM) and ligands for αVβ3 integrin (EDIL3 and POSTN) were expressed at higher levels compared to MG1 and MG5, the latter of which recruit tumour-associated macrophages (TAM) in adult glioblastoma." (PMID 37679810, 2023). "Previous studies have suggested that POSTN secreted by glioblastoma stem cells activates the Akt signalling pathway in macrophages through integrin αvβ3 signalling, leading to macrophage chemotaxis." (PMID 37199594, 2023). "TAp73 controls glioblastoma cell invasion by regulating the expression of the matricellular protein POSTN." (PMID 36980765, 2023). "Previous studies have shown that POSTN secreted by glioblastoma stem cells activates the Akt signalling pathway through integrin αvβ3 signalling, leading to macrophage recruitment." (PMID 37199594, 2023). "Concerning gene and mRNA expression in glioblastoma, Kaplan–Meier curves showed that periostin (POSTN) expression resulted in significantly shorter survival and time to progression." (PMID 35330402, 2022). "ChIP tests indicate that tumor protein 73 (P73) is another transcriptional factor that binds to the promoter of periostin in glioblastoma cells and regulates glioblastoma cell invasion via controlling periostin synthesis." (PMID 36224629, 2022). "It has also been shown that glioblastoma CSCs secrete periostin (POSTN), which binds to integrin αvβ3 and recruits predominantly monocyte-derived macrophages from peripheral blood in glioblastoma mouse models in vivo." (PMID 36613838, 2022). "Another glioblastoma-derived factor influencing TAMs is periostin, which is secreted to recruit TAMs to the tumor." (PMID 34503065, 2021).
glioblastoma (continued). "Studies in other organs, primarily in the context of glioblastoma, have shown increased periostin expression along with increased migratory capacity in pericytes, as a mechanism driving angiogenesis during tumor growth." (PMID 35387027, 2021). "In light of the role of p73 in the regulation of the immune response, it should be noted that in glioblastomas, p73 regulates POSTN expression which in turn promotes M2 macrophage polarisation and tumour growth." (PMID 34944027, 2021). "They demonstrated that p73 conferred an invasive phenotype to glioblastoma cells, which was mediated by activation of POSTN." (PMID 29946533, 2018). "Specifically, we investigated the role of periostin in glioblastoma cell invasion, cell migration and on TGF-β-induced EMT." (PMID 29774119, 2018). "In other instance, glioblastoma stem cells secrete periostin (POSTN) to recruit M2 macrophage-tumour supportive macrophage, and disruption of POSTN leads to the specific inhibition of the tumour-supportive M2 types of TAMs in xenografts." (PMID 29506506, 2018). "In fact, POSTN overexpression was sufficient to rescue the invasive phenotype of glioblastoma cells after p73 knockdown." (PMID 29946533, 2018). "This work investigates the role of periostin in U-87 MG glioblastoma cell invasion, cell migration and in Transforming Growth Factor β (TGF-β)-induced epithelial-mesenchymal transition (EMT)." (PMID 29774119, 2018). "Periostin is a secreted protein that is highly expressed in glioblastoma cells as compared to normal brain tissue, and is therefore considered as a potential biomarker in therapeutic modalities." (PMID 29774119, 2018). "In the current study we demonstrate that p73 promotes invasion and migration in glioblastoma cells through directly activating expression of POSTN." (PMID 26930720, 2016). "We further show that POSTN overexpression is sufficient to rescue the invasive phenotype of glioblastoma cells after p73 knock down." (PMID 26930720, 2016). "We used the Rembrandt database to examine the effect of POSTN mRNA up-regulation on patient survival and found that POSTN overexpression correlates strongly with poor prognosis in glioblastoma patients." (PMID 26930720, 2016). "Taken together this data demonstrates that p73 regulates POSTN levels and thereby invasion of glioblastoma cells." (PMID 26930720, 2016). "Taken together, our results support a novel role of TAp73 in controlling glioblastoma cell invasion by regulating the expression of the matricellular protein POSTN." (PMID 26930720, 2016). "To study the regulation of POSTN by p73, we initially used knock down experiments in U251 and U87 glioblastoma cell lines, where both full p73 and specifically the transcriptionally active TAp73 isoform expression were abolished." (PMID 26930720, 2016). "Here we have demonstrated that TAp73 directly activates POSTN expression leading to an invasive phenotype in glioblastoma cells." (PMID 26930720, 2016). "Several studies have demonstrated that POSTN is up regulated in a variety of tumours, including glioblastoma, and acts as a metastasis-promoting factor." (PMID 26930720, 2016). "Studies have shown that in the hypoxic microenvironment of glioblastoma (GBM), tumor cells can induce tumor-associated macrophages to polarize toward the M2 type through the secretion of paracrine factors such as periostin (POSTN) and exosomes." (PMID 40791576, 2025). "Finally, tumour-associated (M2) macrophages which promote a cancer stem cell phenotype and disease progression, are recruited to murine glioblastoma through expression of the ECM glycoprotein periostin (POSTN)." (PMID 33187209, 2020). "Since POSTN is known to promote invasion of glioblastoma cells we speculated that the reduction of POSTN after p73 knock down is, at least in part, responsible for the loss of invasive ability of the cells." (PMID 26930720, 2016).
glioblastoma (continued). "Moreover, total p73 knock down renders glioblastoma cells more sensitive to Temozolomide treatment and bioinformatic analysis revealed that correlation of p73 and POSTN expression predicts poor patient survival." (PMID 26930720, 2016). "Further studies, especially in vivo, are necessary to establish whether p73 or its target POSTN could provide a drug target for development of new drugs that reduce glioblastoma invasion." (PMID 26930720, 2016). "Meanwhile, in glioblastoma, HIF-1α can increase periostin (POSTN) transcription, promote TANK-binding kinase 1 (TBK1) phosphorylation in ECs, and enhance EC migration and tube formation." (PMID 40821116, 2025). "Periostin is a potent (CCR2+) BMDM recruiter, as evident from studies on glioblastoma and primary melanoma lesions." (PMID 37240029, 2023). "As expected loss of either p73 or POSTN decreased invasion of glioblastoma cells; however, a double knock down of both did not lead to further reduction in invasion, suggesting that indeed both proteins are acting in the same pathway with p73 regulating POSTN expression." (PMID 26930720, 2016). "Here we show that the transcription factor p73 confers an invasive phenotype by directly activating expression of POSTN (periostin, HGNC:16953) in glioblastoma cells." (PMID 26930720, 2016). "CSCs are crucial for monocyte recruitment across tumor types; supernatants from cholangiocarcinoma, hepatocellular carcinoma, or glioblastoma cells under CSC-enriched conditions show elevated levels of tumorigenic macrophage factors like CCL2, CCL5, CSF1, GDF15, IL-13, TGFβ, periostin, and WISP1." (PMID 39068459, 2024). "Meanwhile, crosstalk between M2-like macrophages and PCs in glioblastoma (GBM) promotes PC recruitment and upregulates the expression of the proangiogenic ECM component periostin deposition in PCs through the CECR1–PDGF-B–PDGFR-β signaling pathway." (PMID 34179005, 2021).
melanoma (42 papers, 2007 to 2025). A malignant, usually aggressive tumor composed of atypical, neoplastic melanocytes. "In tumor bearing, Stab1 deficient mice an accumulation of POSTN was predominantly seen in the matrix of Wt31 melanoma metastases (p = 0.0159)." (PMID 38275881, 2024). "In the murine model, accelerated B16F10 melanoma growth was significantly associated with the intensity of periostin expression and the number of infiltrated M2 macrophages." (PMID 30621220, 2019). "Even though melanoma cells are able to produce periostin, tumor-associated stromal fibroblasts are the major source of its production." (PMID 30621220, 2019). "Given that POSTN produced by cancer-associated fibroblasts was recently shown to promote proliferation of melanoma cells by activating MAPK signaling, we also examined the possible effects of POSTN, COL-I, and FN on melanoma cell proliferation." (PMID 26083413, 2015). "The intensity of stromal periostin expression was also significantly associated with the number of infiltrated M2 macrophages, and the number of infiltrated M2 macrophages was associated with the poor prognosis of melanoma patients." (PMID 30621220, 2019). "Moreover, the histological invasiveness and lymph node metastasis of melanoma are significantly associated with stromal periostin expression." (PMID 30621220, 2019). "The high level of periostin expression in primary cultures of skin fibroblasts suggests that fibroblasts may contribute for a large part to periostin production in melanoma-associated stroma." (PMID 18086302, 2007). "POSTN expression is associated with aggressive tumor features, i.e. with poor prognosis and metastatic dissemination, in a variety of cancers, including pancreatic, biliary tract, colorectal, oesophageal, head and neck, lung, breast, ovarian, and genito‐urinary carcinomas, and melanoma." (PMID 36102377, 2022). "Clinical studies on POSTN expression have shown that elevated levels of serum POSTN or tissue POSTN are associated with the increased malignant behavior of multiple types of cancer, such as melanomas, lung metastases, and colon, pancreatic, esophageal, and ovarian cancers." (PMID 33919736, 2021). "Despite the known differences between mouse and human immune systems, one of these markers, SPP1, was also induced by POSTN both in murine macrophages in culture and in intratumoral macrophages in a mouse melanoma model." (PMID 38942020, 2024). "In summary, overexpression of POSTN in melanoma led to a high number of intratumoral SPP1+ macrophages, which was associated with a significantly reduced response to targeted therapy." (PMID 38942020, 2024). "show that expression of the secreted factor POSTN fosters targeted therapy resistance in melanoma by promoting the emergence of a tumor-cell-protective macrophage population." (PMID 38942020, 2024). "The annexin V cell death assay showed that POSTN-induced TTR macrophages significantly prevented MEKi-induced cell death in melanoma cells, in contrast to naive macrophages." (PMID 38942020, 2024). "The results above raise the possibility that POSTN or MDK expression in melanoma mediate emergence of TTR macrophages and, as a consequence, resistance formation." (PMID 38942020, 2024). "POSTN polarizes human macrophages toward a TTR phenotype and promotes resistance to targeted therapy in a melanoma mouse model, which is associated with a phenotype change in intratumoral macrophages." (PMID 38942020, 2024). "Periostin (POSTN) is produced in the lesions surrounding melanoma cell nests in metastatic melanoma." (PMID 37525217, 2023). "In cutaneous melanoma, several reports suggested a correlation between POSTN expression levels and progression of melanoma, both in humans and in a mouse model." (PMID 35409404, 2022).
melanoma (continued). "For example, the increased stromal expression of periostin was significantly correlated with increased numbers of CD163+ TAMs in inflamed melanoma skin, suggesting that TAMs stimulated by POSTN play a significant role in the development of melanoma." (PMID 35409404, 2022). "More recently, RNA-Seq analysis showed that POSTN plays a central role in angiogenesis and anchorage-independent growth of melanoma." (PMID 35409404, 2022). "The stromal expression of periostin was significantly enhanced in the melanomas developed in the inflamed mice compared with those in the control mice." (PMID 30621220, 2019). "We then immunohistologically examined the expression of periostin and infiltrated M2 macrophages in human melanomas, and demonstrated that the intensity of periostin expression was indeed inversely correlated with prognosis in patients with melanoma." (PMID 30621220, 2019). "Various doses of periostin (100 to 1000 ng/mL) significantly promoted the proliferation of B16F10 melanoma cells on day 3 and day 4 in a dose-dependent manner." (PMID 30621220, 2019). "During melanoma tumorigenesis, small but detectable amounts of stromal periostin were detected by immunohistochemistry, even in the control mice." (PMID 30621220, 2019). "We next compared the expression of periostin and infiltrated cells in melanomas developed in control and inflamed skin." (PMID 30621220, 2019). "A recent study using B16F10 melanoma cells deficient in CCN2 (connective tissue growth factor) also highlighted the importance of periostin for melanoma metastasis." (PMID 30621220, 2019). "In conclusion, stromal periostin and the number of CD163+ M2 macrophages are mutually correlated risk factors for a poor outcome in patients with melanoma." (PMID 30621220, 2019). "In human melanomas, high periostin expression and a large number of infiltrated M2 macrophages were significantly correlated with poor prognosis." (PMID 30621220, 2019). "The expression of POSTN in in-transit melanoma was augmented in stromal fibroblasts in patients with irAE, especially after nivolumab administration." (PMID 29643991, 2018). "The tumor stroma of melanoma had increased expression of POSTN upon administration with nivolumab, and POSTN stimulated TAMs to release CXCL5." (PMID 29643991, 2018). "Together, these reports suggest the significance of chemokines from TAMs that can be induced by POSTN in the tumor stroma to induce melanoma-specific TILs in patients with melanoma." (PMID 29410946, 2018). "In metastatic melanoma, periostin (POSTN) is expressed in the region surrounding melanoma cell nests in metastatic melanoma lesions that develop at the wound site." (PMID 29410946, 2018). "In contrast, the expression of POSTN in in-transit melanoma from irAE-developed patients before administration of nivolumab and in-transit melanoma from non-irAE-developed patients was low in fibroblasts distributed in peritumoral lesions." (PMID 29643991, 2018). "Previous investigations using the monoclonal periostin-blocking antibody OC-20 in a murine model of human melanoma show that OC-20 significantly inhibits tumor growth and angiogenesis." (PMID 28977942, 2017). "Periostin (POSTN), frequently overexpressed in melanoma, pancreatic, esophageal, prostate, and liver cancer, promotes invasiveness and metastasis of PDAC and other cancer types." (PMID 26993610, 2016). "Periostin promotes the proliferation of melanoma cells via binding integrin αvβ3 and αvβ5 and activating the p43/p44 MAPK signalling pathway." (PMID 27515461, 2016). "Immunohistochemical staining revealed POSTN expression in the tissue surrounding melanoma tumor cell nests at the metastatic lesions of mice injected with shControl MC3T3-E1 cells." (PMID 26083413, 2015). "Immunohistochemical analysis of the metastatic lesions revealed that POSTN was highly expressed at the periphery of the melanoma tumor cell nests." (PMID 26083413, 2015).